VAPB (VAMP associated protein B and C)
Diseases named in the same sentence as VAPB in open-access papers (continued):
Sharing a sentence is not in itself a finding about the gene and the disease.
medulloblastoma (3 papers, 2023 to 2025). A malignant, invasive embryonal neoplasm arising from the cerebellum. "In line with our previous findings, we found that increased VAPB expression (VAPBhigh) is associated with reduced overall medulloblastoma patient survival." (PMID 37945695, 2023). "We conclude that VAPB is required for proliferation of medulloblastoma cells, thus revealing VAPB as a potential therapeutic target for medulloblastoma treatment." (PMID 37945695, 2023). "To better understand how VAPB influences cell proliferation, we next investigated the consequences of VAPB absence on cell cycle dynamics of our medulloblastoma lines." (PMID 37945695, 2023). "In this study, we explore the potential role of VAPB in the context of cancer using medulloblastoma cell lines." (PMID 37945695, 2023). "By focusing on VAPB and its effects on cellular behavior, we provide a foundation for future investigations to unravel the mechanisms governing medulloblastoma and identify potential avenues for therapeutic interventions." (PMID 37945695, 2023). "Consistent with this clinical correlation, we find that VAPB is required for normal proliferation rates of medulloblastoma cells in vitro and in vivo." (PMID 37945695, 2023). "Here we demonstrate that high VAPB expression in medulloblastoma correlates with decreased overall patient survival." (PMID 37945695, 2023). "As such, we leverage medulloblastoma cell lines as a tool to investigate the potential intersections between VAPB and pathways that hold relevance for both neurodevelopment and the progression of cancer." (PMID 37945695, 2023). "On top of that, the cell proliferation rates were dependent on the expression levels of VAPB: the more VAPB protein present, the higher the proliferation rate, underscoring the relevance of VAPB protein for the in vitro expansion of medulloblastoma cells." (PMID 37945695, 2023). "Recent evidence indicates VAPB supports proliferation in medulloblastoma cells." (PMID 41462933, 2025). "Therefore, medulloblastoma is an interesting model to investigate the possible relationship between VAPB and tumorigenesis." (PMID 37945695, 2023). "Therefore we evaluated VAPB expression in medulloblastoma patient samples according to their subtype, using Cavalli’s dataset." (PMID 37945695, 2023). "To confirm whether the reconstitution of VAPB expression would recover the proliferation of cultured VAPBKO medulloblastoma cells, we overexpressed HA-tagged VAPB under control of a Tet-On (i.e. doxycycline-sensitive) promoter." (PMID 37945695, 2023). "To explore VAPB function in medulloblastoma, we employed two distinct medulloblastoma cell lines." (PMID 37945695, 2023). "In our pursuit to elucidate the implications of VAPB, we turned our focus to medulloblastoma – a suitable choice due to its origins from neural progenitor cells, its scarcity of safe and effective treatments, and the compelling need to unravel novel pathways for potential therapeutic avenues." (PMID 37945695, 2023). "To test whether this interaction also exists in medulloblastoma cell lines, we used our previously generated medulloblastoma cell lines expressing HA-tagged VAPB and performed co-immunoprecipitation as well as PLA assays using HA and EPHA4 as bait." (PMID 37945695, 2023). "However, the expression levels of VAPB might be distinct between medulloblastoma molecular subtypes." (PMID 37945695, 2023). "We conclude that VAPB expression is an important parameter for medulloblastoma growth, particularly in vitro and, therefore, further explored VAPBKO cells to better understand the molecular role of VAPB in medulloblastoma biology." (PMID 37945695, 2023). "Our findings highlight the necessity to further confirm a relation of VAPB protein expression and EPHA4 phosphorylation status in primary human medulloblastoma samples." (PMID 37945695, 2023).
medulloblastoma (continued). "Here we find that absence of VAPB decreases the proliferation potential of medulloblastoma cells in vivo and in vitro due to a cell-cycle delay." (PMID 37945695, 2023). "As we could not find evidence for a direct interaction between VAPB and EPHA4, in medulloblastoma cells, we then investigated whether the absence of VAPB would affect the expression or phosphorylation of EPHA4." (PMID 37945695, 2023).
cardiac arrhythmia (2 papers, 2018 to 2022). Any disturbances of the normal rhythmic beating of the heart or MYOCARDIAL CONTRACTION. "In addition, VAPB might be relevant for inherited forms of ventricular arrhythmias or for arrhythmias in heart failure, in which increased ventricular If current densities are discussed as a major trigger." (PMID 29879376, 2018).
distal hereditary motor neuropathies (2 papers, 2018 to 2022). "Autosomal dominant mutations in VAPB were reported in several families world-wide with clinical presentations of ALS (ALS8) or distal spinal muscular atrophy." (PMID 29648643, 2018).
glioma (2 papers, 2022 to 2023). A benign or malignant brain and spinal cord tumor that arises from glial cells (astrocytes, oligodendrocytes, ependymal cells). "We also demonstrated that overexpression of A-to-I edited miR-497-5p downregulated the expression of OPA1 and VAPB, and repressed proliferation of glioma cells." (PMID 36611869, 2022). "Furthermore, overexpression of A-to-I edited miR-497-5p downregulates OPA1 and VAPB in two cell lines, and inhibits proliferation of glioma cells." (PMID 36611869, 2022). "To further validate that hsa-mir-497_25g repressed OPA1 and VAPB, we transfected p497_25g into two glioma cell lines, i.e., U-118-MG and Hs683, and examined the expression levels of OPA1 and VAPB with quantitative RT-PCR (qRT-PCR) experiments." (PMID 36611869, 2022).
liposarcoma (2 papers, 2009 to 2014). A usually painless malignant tumor that arises from adipose tissue. "Additional genes that cause dominantly inherited forms of clinically typical ALS include the vesicle associated membrane protein (VAMP)-associated protein B (VAPB) (ALS8), the TAR DNA binding protein (TARDBP) and the fused in sarcoma/translated in liposarcoma (FUS/TLS)." (PMID 19479031, 2009).
ovarian carcinoma (2 papers, 2020 to 2021). A malignant neoplasm originating from the surface ovarian epithelium. "ER-mitochondria tethering proteins including VDAC, IP3R1, IP3R2, VAPB, FAM82A2, and GRP75 were also activated in β-sitosterol-incubated ovarian cancer cells." (PMID 34679718, 2021). "In addition, the expression of other ER–mitochondria tethering proteins such as VAPB-PTPIP51 and MFN2 increased in eupatilin-treated ovarian cancer cells." (PMID 32503295, 2020).
sarcoma (2 papers, 2009 to 2021). A usually aggressive malignant neoplasm of the soft tissue or bone. "The loss of VAPB/PTPIP51 interaction occurs through increased activation of GSK3β, as already demonstrated both in TDP-43 or fused in sarcoma (FUS) models, although the mechanism is still obscure." (PMID 34769284, 2021).
atherosclerosis (1 paper, 2021). A disease characterized by the build-up of fatty material and calcium deposition in the arterial wall resulting in partial or complete occlusion of the arterial lumen. "Existing studies have not found that VAPB or PTPIP51 are directly related to the progression of atherosclerosis." (PMID 34336087, 2021).
Atrophy (1 paper, 2024). Any weakening or degeneration, especially through lack of use. "Overall cervical cord atrophy was detected in pre-symptomatic VAPB carriers, and cervical cord WM was atrophy identified in pre-symptomatic C9orf72 hexanucleotide repeat expansion carriers." (PMID 39596864, 2024).
Bradycardia (1 paper, 2018). A slower than normal heart rate (in adults, slower than 60 beats per minute). "Surface ECG recordings of VAPB−/− mice revealed a sino-atrial bradycardia, as heart rates were reduced while the duration of the PQ interval, corresponding to atrio-ventricular conduction, was unchanged." (PMID 29879376, 2018).
cerebral infarction (1 paper, 2024). An ischemic condition of the brain, producing a persistent focal neurological deficit in the area of distribution of the cerebral arteries. "The results show that the PI3K activator can partially reverse the aggravation of injury in CIRI mice induced by VAPB or PTPIP51 reduction, which is manifested by attenuating oxidative stress and autophagy, reducing cerebral infarction volume and improving neurological function." (PMID 38584329, 2024).
Cerebral ischemia (1 paper, 2024). Restriction of arterial blood supply to the brain associated with insufficient oxygenation to support the metabolic requirements of the tissue. "We aimed to investigate the role of MAMs tethering protein VAPB‐PTPIP51 in experimental cerebral ischemia." (PMID 38584329, 2024). "In this study, we employed an in vivo middle cerebral artery occlusion (MCAO) model to simulate cerebral ischemia–reperfusion injury (CIRI) and investigated the structure changes in MAMs mediated by VAPB‐PTPIP51, exploring their potential involvement in the pathological processes of IS." (PMID 38584329, 2024).
cystic fibrosis (1 paper, 2025). Autosomal recessive disorder caused by pathogenic variants in the CFTR gene (cystic fibrosis transmembrane conductance regulator), which encodes a chloride and bicarbonate channel expressed in epithelial cells, and follow the diagnosis criteria. "Lung infection in cystic fibrosis elevates VAPB-PTPIP51 tethering, amplifying inflammation." (PMID 41367495, 2025). "In cystic fibrosis, P. aeruginosa infection in bronchial cells from cystic fibrosis patients enhanced VAPB-PTPIP51 tethering at MAMs, disrupting autophagy and increasing mitochondrial Ca2+ uptake, which triggers NLRP3 inflammasome activation and hyperinflammation." (PMID 41367495, 2025).
distal arthrogryposis (1 paper, 2018). A muscle tissue disease characterized by congenital joint contractures of hand and feet. "Expression of several genes linked to motor neuronopathy and familiar amyotrophic lateral sclerosis (EPHA4, IGHMBP2, VAPB, BICD2, and DYNC1H1) or distal arthrogryposis (MYH8, ZC4H2, MUSK, RAPSN) were significantly upregulated or downregulated." (PMID 29727687, 2018).
fibrosis (1 paper, 2025). the formation of excess fibrous connective tissue in an organ or tissue in a reparative or reactive process. "SiO2 disrupts VAPB-PTPIP51 tethering during progression of lung injury and fibrosis." (PMID 41367495, 2025).
Glucose intolerance (1 paper, 2023). Glucose intolerance (GI) can be defined as dysglycemia that comprises both prediabetes and diabetes. "Consistently, ablation of VAPB in mice led to downregulation of IRS-1, suppression of insulin signaling, and glucose intolerance." (PMID 37528084, 2023).
invasive ductal carcinoma (1 paper, 2012). "We observed a significant increase of VAPB expression in invasive ductal carcinoma and lymph node metastasis samples, compared to normal tissue (p<0.01, Chi-square test)." (PMID 23049696, 2012).
ischemic stroke (1 paper, 2024). A stroke disorder caused by obstruction of blood flow to the brain, due to thrombotic (local blood clot formation) or embolic (due to a blood clot or other material traveling from another site) event. "The downregulation of VAPB‐PTPIP51 expression after ischemic stroke mediates structural damage to mitochondria‐associated endoplasmic reticulum membranes, which may exacerbate CIRI by regulating the PI3K pathway and activating autophagy." (PMID 38584329, 2024).
lipid metabolism disorders (1 paper, 2025). "Targeting lipid transport proteins such as StARD3 or VAPB may reduce neuroinflammation caused by lipid metabolism disorders." (PMID 41456957, 2025).
lung adenocarcinoma (1 paper, 2013). A carcinoma that arises from the lung and is characterized by the presence of malignant glandular epithelial cells. "Some of the genes such as PIK3CA, TAF15, VAPB, Appl1, Rab5a, ARF4, and XIAP in Merged-module activate the PI3K-Akt pathway and are overexpressed in a manner similar to that of EGFR in lung adenocarcinoma." (PMID 23874428, 2013).
lymphadenitis (1 paper, 2016). Acute or chronic inflammation of one or more lymph nodes. "No vapB-positive strains were detected and from the cases of lymphadenitis in cattle in Ireland and Germany." (PMID 27234339, 2016).
neuropathy (1 paper, 2018). A disorder affecting the nervous system that manifests with pain, tingling, numbness, and/or muscle weakness. "iNPCs carrying a neuropathy-related dominant GARS mutation showed reduced VAPB and its downstream pathways, including altered mitochondrial and cellular calcium homeostasis, providing a potential explanation for neuron-specific clinical manifestations." (PMID 29648643, 2018).
prostate adenocarcinoma (1 paper, 2025). "Analysis of The Cancer Genome Atlas prostate adenocarcinoma cohort (TCGA-PRAD) revealed that VAPB mRNA expression is significantly higher in prostate cancer tissues compared to normal prostate tissues." (PMID 41462933, 2025).
prostate carcinoma (1 paper, 2025). A carcinoma that arises from epithelial cells of the prostate gland. "These in silico findings provide additional evidence that VAPB is upregulated in prostate cancer, consistent with the loss of its miRNA-mediated repression in tumors." (PMID 41462933, 2025). "To support the relevance of VAPB in prostate cancer, we performed an in silico validation using public gene expression datasets." (PMID 41462933, 2025). "Mutations in VAPB in familial neurodegenerative disease ALS patients were identified, but its relevance to prostate cancer was identified via bioinformatic analysis of miRNA targets." (PMID 41462933, 2025). "The downregulation of several tumor-suppressive miRNAs (with concomitant upregulation of oncogenic miRNAs) in prostate cancer may contribute to malignancy—including the de-repression of novel targets like VAPB, which we identify as a promising new biomarker and therapeutic target." (PMID 41462933, 2025). "Consistent with this, analysis of independent datasets indicates that VAPB transcript levels are higher in primary prostate tumors than in benign or normal prostate tissues (as evidenced by TCGA data), supporting the idea that VAPB is indeed upregulated in prostate cancer." (PMID 41462933, 2025). "Since VAPB has not been widely studied in prostate cancer, it represents a promising, novel candidate for both diagnosis and therapeutic targeting." (PMID 41462933, 2025).
prostate tumors (1 paper, 2025). "Similarly, examination of an independent gene expression microarray dataset from GEO indicated that VAPB transcript levels are elevated in prostate tumor samples relative to benign prostate samples." (PMID 41462933, 2025).
neurodegenerative disease (23 papers, 2013 to 2025). A disorder of the central nervous system characterized by gradual and progressive loss of neural tissue and neurologic function. "GSK3β is strongly implicated in neurodegenerative diseases and is a negative regulator of the VAPB-PTPIP51 interaction." (PMID 40045432, 2025). "Recent studies linked the interaction of PTPIP51/VAPB to the GSK3β activation status in a neurodegenerative disease, namely ALS." (PMID 28754031, 2017). "Like many proteins linked to neurodegenerative diseases, mutant VAPB forms intracellular inclusions." (PMID 25409455, 2014). "Thus, the findings we report here pave the way for future studies that address whether synaptic damage in neurodegenerative diseases is linked to changes in VAPB-PTPIP51 interactions and ER-mitochondria signaling." (PMID 30841933, 2019). "A number of lines of evidence suggest that this disruption to the VAPB-PTPIP51 interaction is a driver of neurodegenerative disease." (PMID 40045432, 2025). "A better understanding of the pathways linking neurodegenerative disease insults to GSK3β activation, VAPB-PTPIP51 phosphorylation and binding would progress this important field." (PMID 40045432, 2025). "The involvement of key proteins such as Sig‐1R, IP3R, and VAPB in maintaining ER‐mitochondrial communication and their dysfunction in neurodegenerative diseases is emphasized." (PMID 40406921, 2025). "The involvement of the VAPB-PTPIP51 tethers in neurodegenerative disease has been most intensively studied in FTD/ALS." (PMID 40045432, 2025). "Damage to the VAPB-PTPIP51 tethers is also seen in neurodegenerative diseases and so the use of neuronal SH-SY5Y cells is relevant in this context." (PMID 36120587, 2022). "Our findings that the VAPB-PTPIP51 tethers regulate synaptic activity therefore provide a novel route linking neurodegenerative disease insults with synaptic dysfunction." (PMID 30841933, 2019). "This behavior distinguishes VAPB inclusions from the “classical” aggregates of neurodegenerative diseases." (PMID 26287246, 2015). "Such information would also facilitate the design of small molecules that might rescue damaged VAPB-PTPIP51 tethers in neurodegenerative diseases." (PMID 40045432, 2025). "Moreover, we show that ursodeoxycholic acid (UDCA), an FDA approved drug linked to FTD/ALS and other neurodegenerative diseases therapy and whose precise therapeutic target is unclear, corrects TDP43 linked damage to the VAPB-PTPIP51 interaction." (PMID 38395965, 2024). "It will therefore be interesting to determine whether there are links between neurodegenerative disease insults, the VAPB-PTPIP51 tethers, and autophagy." (PMID 28132811, 2017). "Since GSK-3β is also strongly implicated in AD and PD 75, 76, alterations to GSK-3β activity may be a common mechanism for disrupting the VAPB–PTPIP51 tethers and ER–mitochondria associations in at least some forms of neurodegenerative disease." (PMID 26899735, 2016). "Interestingly, ASNA1 has been shown to bind to VAPB, although a role in human neurodegenerative diseases has still to be investigated." (PMID 26362251, 2015). "Thus, the beneficial effects of UDCA in FTD/ALS and other neurodegenerative diseases may involve at least in part, correction to damaged VAPB-PTPIP51 tethering and ER-mitochondria signaling via inhibition of GSK3β." (PMID 38395965, 2024). "Thus, there appears to be different routes by which neurodegenerative disease insults can impact upon ER–mitochondria tethering via the VAPB–PTPIP51 interaction, some involving activation of GSK-3β and some such as we describe here for α-synuclein, involving binding to the tethering proteins." (PMID 28337542, 2017). "Considering the role of the VAPB-PTPIP51 tethers in several key cellular functions and that disruption of the interaction is seen in major neurodegenerative diseases, such work should be a priority." (PMID 36120587, 2022).